GDF15 (growth differentiation factor 15)
Diseases named in the same sentence as GDF15 in open-access papers (continued):
Sharing a sentence is not in itself a finding about the gene and the disease.
COVID-19 (continued). "Regarding the validity of serum GDF-15 level to discriminate children with COVID-19 from controls, its sensitivity was 79.17%, and its specificity was 100.0%, at a cut-off > 272.8 pg/mL." (PMID 37974205, 2023). "In summary, GDF-15 serves as an important biomarker in COVID-19, providing insights into disease severity and predicting clinical outcomes." (PMID 37568870, 2023). "While, regarding the validity of serum GDF-15 level to assess cardiac affection of COVID-19 children, its sensitivity was 92.31%, and its specificity was 95.74% at a cut-off > 873.16 pg/mL." (PMID 37974205, 2023). "Further research and clinical trials are necessary to determine the utility and safety of GDF15-related interventions in children with COVID-19." (PMID 37974205, 2023). "Clusters 2 (n = 23) and 3 (n = 21) represent COVID-19 patients with the highest IL-1β (with low sRAGE and GDF15) and lactoferrin (and high Fec and GDF15), respectively." (PMID 37582864, 2023). "In children with COVID-19, increased GDF-15 was correlated to poorer ejection fraction and higher INR using multivariate linear regression analysis." (PMID 37974205, 2023). "This study aimed to measure the level of serum growth differentiation factor (GDF-15) in children with COVID-19 and to correlate it with the disease severity, cardiac affection, and the outcome of COVID-19." (PMID 37974205, 2023). "Mean plasma levels of IL-1β and IL-18, as products of inflammasome activity and pyroptosis, were higher in COVID-19 than in the other groups, as was the case for the alveolar cell damage marker sRAGE and GDF15 in the COVID-19 group." (PMID 37582864, 2023). "Serum GDF-15 is a promising biomarker of COVID-19, it can be used as a predictor of cardiac manifestations in children with COVID-19 and severe disease." (PMID 37974205, 2023). "A retrospective study comprised 111 COVID-19 patients compared to 20 healthy controls revealed that the GDF15 serum was correlated with critical patients, but decreased in recovered COVID-19 patients at the time of discharge." (PMID 36140453, 2022). "An observational study involving 66 hospitalized COVID-19 patients demonstrated that both GDF15 and calprotectin serum levels were increased and correlated with disease severity and mortality." (PMID 36140453, 2022). "GDF-15 has emerged as an immune modulator in older patients with anemia in COVID-19 and its role is critical in ferroptosis and dysregulated hematopoiesis in the erythroid cell lineage." (PMID 35251002, 2022). "A retrospective study comprising 2623 confirmed COVID-19 patients with acute hepatic injury revealed that low albumin serum level and high GDF15 serum level are correlated with COVID-19 severity and death." (PMID 36140453, 2022). "GDF-15 is secreted from the epithelial and endothelial cells as a result of inflammation and oxidative stress in COVID-19." (PMID 35251002, 2022). "GDF15 serum level increased in parallel with calprotectin a biomarker of GIT injury in critically affected COVID-19 patients." (PMID 36140453, 2022). "GDF15 has a similar prognostic value to that of calprotectin in the prediction of COVID-19 complications and severity." (PMID 36140453, 2022). "The rising of GDF15, galectin-9 and C3a in COVID-19 patients reflect intestinal tight junction dysfunction with translocation of intestinal microbes into the circulation with the development of systemic inflammation." (PMID 36140453, 2022). "GDF-15 integrates information on cellular oxygenation, inflammatory response and cardio-renal dysfunction, which are all key mechanisms in COVID-19 pathophysiology, suggesting GDF-15 as an ideal candidate as a prognostic marker in COVID-19." (PMID 36552007, 2022). "In conclusion, critically ill patients with COVID-19 present higher levels of GDF15 and ACE2, as well as acute inflammation." (PMID 35937703, 2022). "GDF15 serum level is increased in COVID-19 patients with extra-pulmonary manifestations including GIT injury and acute hepatic damage." (PMID 36140453, 2022).
COVID-19 (continued). "Despite its involvement in immune tolerance, GDF-15 elevation seems to be overwhelmed by uncontrolled inflammation in certain patients with COVID-19, leading to vascular pathologies in vital organs." (PMID 35251002, 2022). "Of interest, growth differentiation factor 15 (GDF15) has been recently to be a potential biomarker correlated with COVID-19 severity." (PMID 36140453, 2022). "In COVID-19, GDF-15 activity represents a strong predictor of poor outcomes in critically ill patients acting as a central mediator of inflammation." (PMID 36552007, 2022). "In comparison with well-known biomarkers of COVID-19, the GDF15 is increased in parallel with other inflammatory biomarkers in COVID-19 patients." (PMID 36140453, 2022). "COVID-19 patients have elevated GDF-15 levels, suggesting a potential link between GDF-15 and disease severity in the ongoing pandemic." (PMID 35821815, 2022). "In this review, we discuss the emergence of GDF-15 as a distinctive marker of viral infection severity, especially in the context of COVID-19." (PMID 35251002, 2022). "A retrospective study that included 440 COVID-19 patients showed that the GDF15 serum level was increased and positively correlated with C reactive protein (CRP), IL-6 and IL-8 in severely affected patients." (PMID 36140453, 2022). "The role of GDF-15 in viral pathogenesis, notably COVID-19, seems to be context-dependent, spanning from a promotor of disease tolerance in the early phase of infection to a detrimental actor in certain patients with cytokine storm." (PMID 35251002, 2022). "The present study explores the association between GDF-15 and in-hospital mortality among CKD patients hospitalized for COVID-19." (PMID 36552007, 2022). "The gut was not an exception and the defensin HD5, the calprotectin S100A8/A9 and the GDF-15 had a specific role both in the gastroenterological manifestation and the prognosis of COVID-19." (PMID 34042528, 2021). "In COVID-19 patients treated in the ICU, the GDF-15 level was associated with the time to wean off MV and better predicted late recovery." (PMID 35095877, 2021). "At six months post-infection, GDF-15 concentration remained significantly higher in the severe and moderate COVID-19 groups, compared to patients with mild COVID-19 and controls (p < 0·05, ANCOVA)." (PMID 34333238, 2021). "Our results showed that serum GDF-15 levels were increased in patients with COVID-19 and also correlated with other biomarkers of severity." (PMID 34829345, 2021). "In this study, we derived three cytokines, IL-6, amphiregulin, and GDF-15, that were related to disease severity in COVID-19 and compared these cytokines between COVID-19 and sepsis." (PMID 35095877, 2021). "Both those parameters were correlated (r = 0.424; p < 0.001), and GDF-15 levels also correlated with other biomarkers of COVID-19 severity/mortality, namely, IL-6, CRP, ferritin, D-dimer and neutrophils, and inversely with lymphocyte count." (PMID 34829345, 2021). "During the acute phase of COVID-19, patients with severe and moderate disease had markedly higher GDF-15 concentrations compared to individuals with mild disease and to controls (p < 0·001, ANCOVA)." (PMID 34333238, 2021). "In the validation cohort, IL-6 and GDF-15 were elevated in COVID-19 and sepsis on day 1, and the levels of these cytokines were higher in sepsis than in COVID-19." (PMID 35095877, 2021). "For COVID-19, Cox proportional hazard analyses with time as a dependent covariate showed that as the P-value for GDF-15 was <0.05, high GDF-15 was associated with longer time until weaning off MV." (PMID 35095877, 2021). "In COVID-19 patients treated in the ICU, GDF-15 was associated with the time to wean off MV and better predicted late recovery." (PMID 35095877, 2021). "The levels of IL-6 and GDF-15 in sepsis were statistically significantly higher than those in COVID-19 on day 1 to days 6-8, and on day 1 and days 2-3, respectively." (PMID 35095877, 2021).
COVID-19 (continued). "Our finding that GDF-15 levels are higher on admission in longer-stay patients hospitalized with COVID-19 supports a potential role for quantifying GDF-15 as a means of promptly evaluating prognosis in these patients." (PMID 34829345, 2021). "Our aim was to analyse GDF-15 levels in patients with COVID-19 and to correlate them with clinical and laboratory parameters of disease severity." (PMID 34829345, 2021). "Circulating levels of GDF15 have been found to be significantly higher in COVID-19 patients who die45." (PMID 34112877, 2021). "In comparison to those of the healthy controls, the plasma GDF-15 levels of the COVID-19 and sepsis patients were significantly higher on days 1, 2-3, and 6-8." (PMID 35095877, 2021). "After adjusting for three cases with a history of malignancy, the remaining COVID-19 patients still had median GDF-15 levels of 12.4 ng/ml." (PMID 33123167, 2020). "The study aimed to introduce a possible novel biomarker for predicting COVID-19 severity, GDF-15." (PMID 38672113, 2024). "The findings of such studies could help us better understand the pathophysiological mechanisms of GDF-15 release in COVID-19 and in general." (PMID 38672113, 2024). "It is worth noting that it showed an association between elevated levels of GDF-15 and negative outcome in COVID-19 patients." (PMID 38672113, 2024). "Furthermore, a study on autopsy lungs and plasma samples correlated GDF-15 levels with tissue damage and fibrotic remodelling of the lungs in COVID-19 patients." (PMID 38672113, 2024). "In COVID-19+ patients, we found a strong correlation between GDF-15 and soluble CD48 levels." (PMID 38686386, 2024). "Elevated serum GDF-15 levels in the acute phase of COVID-19 may act as a predictive biomarker with the onset of long COVID, which enables early identification and management, thereby improving outcome." (PMID 38826986, 2024). "In this study, elevated serum GDF-15 levels suggested that mitochondrial modulation in the acute phase may influence the subsequent course of COVID-19." (PMID 38826986, 2024). "Since studies are scarce, it is imperative to continue research on this topic with larger patient cohorts to fully understand the potential of GDF-15 as a biomarker of COVID-19 severity and to recognize its pathophysiological pathways in this disease, as well as in others." (PMID 38672113, 2024). "This study confirms GDF-15 as a biomarker for COVID-19 severity." (PMID 38686386, 2024). "More precisely, GDF-15 levels could also be measured after the clinical resolution of COVID-19, and it remains to be determined whether the levels of GDF-15 will decrease to their basal values." (PMID 38672113, 2024). "GDF15 is a biomarker with prognostic importance in patients with sepsis and COVID-19." (PMID 38725041, 2024). "Questions regarding the dynamics of GDF-15 elevation and its time interval for chronic diseases, pregnancy, adiposity, and other prolonged clinical states, as well as the same questions for acute diseases such as COVID-19 and sepsis, remain to be pondered." (PMID 38672113, 2024). "Observed GDF-15 levels were able to predict COVID-19 disease severity (AUC=0.82 ± 0.02, p<0.0001)." (PMID 38686386, 2024). "Considering its capacity to induce hypoxia and characteristic high expression in endothelial cells, GDF15 may also participate in COVID-19 endothelial inflammation." (PMID 37093513, 2024). "Further research is needed, including that into which tissues express GDF-15 in COVID-19." (PMID 36331721, 2023). "This evidence may relate to GDF15 as a probable indicator of disease severity in patients infected with COVID-19." (PMID 37408184, 2023). "GDF-15 does not affect susceptibility to COVID-19 in the population, IVW (OR = 1.01, 95% CI 0.99–1.03; P = .35); weighted median (OR = 1.01, 95% CI 0.99–1.04; P = .34); MR-Egger (OR = 0.99, 95% CI 0.92–1.08; P = .95)." (PMID 37773870, 2023).
COVID-19 (continued). "Thus, in real-life situations with hospitalized COVID-19 patients, serial measurements of GDF-15 can be an aid in patient triage and follow disease progression more efficiently." (PMID 37974205, 2023). "Serum GDF-15 level was significantly higher in patients with COVID-19 than in controls (p < 0.01)." (PMID 37974205, 2023). "GDF15 is emerging as a promising field for research in the context of children with COVID-19." (PMID 37974205, 2023). "GDF-15 elevated alongside other inflammatory biomarkers in COVID-19 patients." (PMID 37974205, 2023). "GDF-15 levels have also been shown to correlate with COVID-19 severity." (PMID 37152099, 2023). "Similarly, GDF15, a marker of COVID-19 severity, was minimally expressed in VBT and UNV groups, followed by increasing trend in moderate and severe cases." (PMID 37022180, 2023). "Moreover, elevated GDF-15 levels were observed in COVID-19-related ARDS cases treated in the ICU, particularly among non-survivors." (PMID 37568870, 2023). "GDF-15 has also been shown as a significant predictor for important clinical outcomes in COVID-19." (PMID 37568870, 2023). "Furthermore, a case–control study comprising 80 patients with moderate to severe COVID-19 showed that the GDF15 serum level was increased together with increasing levels of galectin-9 and C3a in severely affected patients." (PMID 36140453, 2022). "Cytokine storm-induced GDF-15 elevation was shown to protect against cardiovascular alterations in a mouse model, however, it remains unknown whether this effect is present in COVID-19 patients." (PMID 35251002, 2022). "However, a study with a larger sample size, and a control study group is needed to completely clarify the possible influence of serum GDF-15 concentrations on outcome COVID-19 patients." (PMID 35464749, 2022). "On the other hand, growth differentiation factor-15 (GDF-15), a member of the TGF-β superfamily implicated in metabolic regulation, also appears to be a strong predictor of poor outcomes in patients with a severe form of COVID-19." (PMID 35956112, 2022). "A Chinese study found that GDF-15 concentrations correlated with the severity of COVID-19 and the changes in its concentrations were closely associated with the disease progression so it might serve as a new biomarker for disease severity." (PMID 35464749, 2022). "Of interest, GDF15 could be a promoter of COVID-19 tolerance in the early phase of SARS-CoV-2 infection to a detrimental factor in the propagation of the cytokine storm." (PMID 36140453, 2022). "On the other hand, serum GDF-15 levels (OR 1.037, 95% CI 1.022–1.054, p < 0.001) and leukocyte count (OR 1.077, 95% CI 1.003–1.157, p =0.008) were the significant positive predictors for a fatal COVID-19 outcome." (PMID 35956112, 2022). "These verdicts proposed that GDF15 could be a diagnostic and prognostic biomarker of GIT injury in COVID-19." (PMID 36140453, 2022). "Taken together, in virtue of its anti-inflammatory effects, GDF15 may inhibit the propagation of cytokine storm in COVID-19 patients through modulation of the immune-inflammatory response and attenuation of the exaggerated immune response." (PMID 36140453, 2022). "Moreover, recent studies conducted on COVID-19 patients found that tissue damage and hypoxia consequently respond with a significant rise in GDF-15 activity." (PMID 35956112, 2022). "Furthermore, median levels of CRP, GDF-15, IL-6, and sFlt-1 increased with COVID-19 disease severity, whereas the median level of sACE2 decreased with COVID-19 disease severity." (PMID 35453934, 2022). "Furthermore, multivariate logistic regression showed that catestatin, GDF-15 and leukocyte count were significant predictors for COVID-19 survival." (PMID 35956112, 2022). "GDF-15 could therefore potentially be used as a critical biomarker to predict the early use of iron-chelating therapy in patients with COVID-19 with co-existing subclinical inflammation and complications." (PMID 35251002, 2022).
COVID-19 (continued). "Similarly, GDF-15 has also been studied in COVID-19, where it was successfully proven to be of predictive value for important clinical outcomes." (PMID 35326373, 2022). "Increased GDF15 could be a compensatory mechanism against hyperinflammation and exaggerated immune response in the COVID-19." (PMID 36140453, 2022). "Interestingly, growth differentiation factor 15 (GDF15) has recently become a potential biomarker correlated with the COVID-19 severity." (PMID 36140453, 2022). "However, circulating levels of GDF-15 can predict the in-hospital mortality in COVID-19 patients from the recent study." (PMID 35784345, 2022). "All of this evidence pointed out that GDF-15 could be a strong predictor of COVID-19 severity and poor outcomes." (PMID 35956112, 2022). "A small size prospective study involved 58 survivor COVID-19 patients compared to 8 non-survivor COVID-19 patients showed that a higher GDF15 serum level was associated with higher mortality." (PMID 36140453, 2022). "Interestingly, Myhre and colleagues confirmed in a prospective observational study that the GDF15 offers a prognostic biomarker superior to other inflammatory biomarkers in unselected hospitalized COVID-19 patients." (PMID 36140453, 2022). "It has been shown that the GDF15 serum level is correlated with the COVID-19 severity." (PMID 36140453, 2022). "A longitudinal study including patients with end-stage kidney disease with/without COVID-19 revealed that GDF15 was regarded as a novel biomarker linked with the COVID-19 severity." (PMID 36140453, 2022). "A relationship between GDF15 and COVID-19 was reported recently." (PMID 34335566, 2021). "Further studies including identification of the site GDF-15 production may clarify whether GDF-15 can be new therapeutic target for critical COVID-19 patients." (PMID 35095877, 2021). "In addition, in the search for useful biomarkers to predict COVID-19 outcomes, cytokine growth differentiation factor 15 (GDF-15) was recently proposed as a biomarker of general disease severity and unfavourable outcomes." (PMID 34333238, 2021). "It is important to highlight the potential value of GDF-15 as a prognostic factor for COVID-19." (PMID 34829345, 2021). "First, we could not establish an association between GDF-15 levels and mortality due to the low mortality in our cohort, and second, we did not take serial measurements in order to analyse the possible role of GDF-15 in COVID-19 follow-up." (PMID 34829345, 2021). "We further investigated GDF15 serum levels, and the results suggested that this cytokine may serve as an effective indicator of disease severity in COVID-19 patients." (PMID 34335566, 2021). "In COVID-19, no cytokines were associated with mortality, and only GDF-15 was associated with late recovery." (PMID 35095877, 2021). "In addition, we found a consistent increase in GDF15 levels with increasing disease severity among the asymptomatic, mild, moderate, and severe groups of COVID-19 patients." (PMID 34335566, 2021). "GDF-15 and IL-6 derived from proteomics analysis were related with disease severity of COVID-19." (PMID 35095877, 2021). "In conclusion, GDF-15 has a potential role in stratifying patients with COVID-19 by severity." (PMID 34829345, 2021). "We determined circulating levels of GDF-15 and correlated them with clinical and laboratory parameters reflecting severity in 84 patients with COVID-19, finding that GDF-15 levels were higher in both patients than in 20 healthy controls and were higher in patients with poorer respiratory function." (PMID 34829345, 2021). "As expected, an association was observed between GDF-15 levels and age in both the COVID-19 and healthy control individuals (data not shown)." (PMID 34829345, 2021). "Inflammation and GDF15 have already been associated, and higher levels of inflammatory blood biomarkers, such as CRP, ferritin, and D-dimers, have been reported as predictors of poor outcomes in COVID-19 patients." (PMID 34445593, 2021).